ASB9 (ankyrin repeat and SOCS box containing 9)
Description:
Substrate-recognition component of a cullin-5-RING E3 ubiquitin-protein ligase complex (ECS complex, also named CRL5 complex), which mediates the ubiquitination and subsequent proteasomal degradation of target proteins. The ECS(ASB9) complex catalyzes ubiquitination of creatine kinases CKB and CKMT1A. [Isoform 2]: Does not interact with the Elongin BC complex, likely to be a negative regulator of isoform 1.
Synonyms: DKFZP564L0862; MGC4954; FLJ20636
Tractability: PROTAC: ubiquitination databases record sites on it.
Gene: Protein-coding gene on chromosome X (15,235,288 to 15,270,467, reverse strand). Ensembl gene ENSG00000102048.
Subcellular location: Mitochondrion
Pathways (Reactome):
Immune System: Antigen processing: Ubiquitination & Proteasome degradation
Metabolism of proteins: Neddylation
Gene Ontology:
Molecular function: protein binding; ubiquitin-like ligase-substrate adaptor activity
Biological process: positive regulation of protein catabolic process; proteasome-mediated ubiquitin-dependent protein catabolic process; protein ubiquitination; intracellular signal transduction
Cellular component: Cul5-RING ubiquitin ligase complex; mitochondrion; cytosol
Homologues: Orthologues: chimpanzee ASB9 (87% identical), pig ASB9 (80% identical), rabbit ASB9 (80% identical), guinea pig ASB9 (74% identical), rat Asb9 (74% identical), mouse Asb9 (73% identical), dog ASB9 (68% identical), tropical clawed frog asb9 (56% identical). Paralogues in human: ASB11 (51% identical), ASB5 (48% identical).
Diseases named in the same sentence as ASB9 in open-access papers:
ASB9 is named in the same sentence as 9 diseases in open-access papers, as found by Europe PMC text mining. Sharing a sentence is not in itself a finding about the gene and the disease. The quoted sentences say what the papers report.
colorectal cancer (3 papers, 2016 to 2023). A primary or metastatic malignant neoplasm that affects the colon or rectum. "ASB9 negatively regulates the proliferation and invasion of colorectal cancer cells." (PMID 36683111, 2023). "Furthermore, high ASB9 mRNA expression is correlated with good prognosis, and knockdown of ASB9 increases colorectal cancer (CRC) cell invasiveness." (PMID 27030794, 2016). "Studies have reported that the expression of mRNA in ASB9 in CRC tissues is higher than that in corresponding normal tissues, and it can be used as an independent prognostic factor for colorectal cancer." (PMID 32547947, 2020).
Alzheimer disease (2 papers, 2014 to 2020). A progressive, neurodegenerative disease characterized by loss of function and death of nerve cells in several areas of the brain leading to loss of cognitive function such as memory and language. "Interestingly, alterations in both ASB9 and FBXW12 have also been associated with Alzheimer's disease (40, –, 42)." (PMID 31911436, 2020).
breast carcinoma (2 papers, 2008 to 2010). "In the present study we identified three breast tumor-associated proteins – ASB-9, SERAC 1 and RELT – from a breast cancer cDNA T7 phage library screening with antibodies in breast cancer sera." (PMID 18460216, 2008). "Recently, ASB9 was isolated as a potential biomarker for breast cancer." (PMID 20302626, 2010). "ASB9 was isolated as a potential biomarker for breast cancer." (PMID 20302626, 2010). "It will be interesting to investigate whether the reported increase of ASB9 expression is derived from upregulation of ASB9ΔSOCS rather than ASB9 in breast cancer cells." (PMID 20302626, 2010).
prostate carcinoma (2 papers, 2008 to 2020). A carcinoma that arises from epithelial cells of the prostate gland. "In this study, ASB9 is highly expressed in prostate cancer, but the mechanism is still unclear." (PMID 32547947, 2020). "We used univariate and multivariate Cox regression analysis to identify seven prognostic signatures for prostate cancer patients, including BCO1, BAIAP2L2, C7, AP000844.2, ASB9, MKI67P1, TMEM272." (PMID 32547947, 2020).
Azoospermia (1 paper, 2023). Absence of any measurable level of sperm,whereby spermatozoa cannot be observed even after centrifugation of the semen pellet. "In addition, we examined the changes in the distribution of ASB9 in non-obstructive azoospermia (NOA) patients using Western blot and immunofluorescence." (PMID 36683111, 2023).
cancer (2 papers, 2010 to 2025). A tumor composed of atypical neoplastic, often pleomorphic cells that invade other tissues. "Two additional investigations that reported ASB9’s involvement in cancer provided evidence of the detrimental effects of ASB9 on cell proliferation." (PMID 41154747, 2025). "Perhaps the regulation of ASB9 and ASB9ΔSOCS expression will be an escaping strategy for cancer cells or established cell lines from the suppressive function of ASB9." (PMID 20302626, 2010).
infection (1 paper, 2013). The state of being infected such as from the introduction of a foreign agent such as serum, vaccine, antigenic substance or organism. "ASB9 could not be detected in the stomach nor the duodenum of the gerbils at 9 weeks after experimental infection, which might indicate that the infection was cleared within 9 weeks, or that ASB9 was not able to colonize the gastric mucosa." (PMID 23895283, 2013).
ASB9 also shares sentences with these, for which no sentence is quoted: breast tumor (1 paper); Obesity (1).